CD4 (CD4 molecule)
Diseases named in the same sentence as CD4 in open-access papers (continued):
Sharing a sentence is not in itself a finding about the gene and the disease.
tumor (continued). "A significant change in the number of tumor-infiltrating CD4+ cells was also observed in the RT/MSC-sTRAIL/anti-PD-L1 group." (PMID 35835756, 2022). "hNPs activated both ICD-induced immune responses and autophagy mediated Th1-type immune responses, increased DC activation efficacy, increased CD8+ and CD4+ T cell population in tumors, effectively inhibited tumor growth, and extended animal survival." (PMID 35303868, 2022). "Immune reactions mediated by CD8+ and CD4+ Th1 lymphocytes play a crucial role in anti-tumor immunity by eliciting specific immune responses to tumors." (PMID 36437379, 2022). "Several studies documented the anti-tumor potency of CD4+ T cells and their role in directing and sustaining efficient anti-tumor immune responses." (PMID 36605208, 2022). "These are an abundant but heterogeneous and dynamic T cell population in the tumor, and TGFβ is a major regulator of CD4+ T cell plasticity." (PMID 36382146, 2022). "In a similar manner to CD8+ T cells, CD4+ T cells were shown to induce direct cytotoxicity against tumor cells in pre-clinical tumor models." (PMID 36605208, 2022). "CD4+ T cells produced the Th1 cytokine IFNγ and the Th2 cytokine IL-4, both of which were required for maximal tumor immunity." (PMID 36159781, 2022). "For example, helper T cell (Th cell), including the Th2, Treg or Th17 lineages, differentiated by CD4+ T cells, play a tumor-promoting role in tumors." (PMID 35309293, 2022). "An analysis of the profile of 22 types tumor infiltrating immune cells demonstrate that the abundance of B cells naïve, T cells CD4 memory resting, Macrophages M2 and Mast cells activated were significantly higher in high-risk group (P < 0.05)." (PMID 35227285, 2022). "CD4+ T cells have long been thought to be tumour suppressors, CD4+ T cells have an intrinsic capacity to stimulate cytotoxic T lymphocytes (CTLs), and Th1 effector cells have been demonstrated to suppress tumour development and promote CTL function." (PMID 35488454, 2022). "It is necessary to conduct in-depth research on the relationship between CD4+T cells accumulation at the tumor margin of CCA and the prognosis." (PMID 36147461, 2022). "A lower count of CD4+CD25+Foxp3+ Tregs in SMGs at Day 14 was detected in tumor-bearing Atg5flox/flox mice, while the Treg counts in spleens from mice with different host autophagy capacity were indistinguishable." (PMID 35966597, 2022). "In SCLC cell lines, Treg generation is induced by CD4 T cells through the production of IL-15, further supporting the notion that tumor cells can manipulate Tregs to their advantage." (PMID 34417572, 2022). "The current challenge consists of modulating CD4+ T cell polarization and promoting appropriate antitumor CD4+ helper T cell recruitment within the tumor." (PMID 35008422, 2022). "CD8+ cytotoxic T-cells directly target tumor cells whereas, CD4+ helper T-cells regulate an immune response by secreting cytokines that stimulate other immune cells." (PMID 35557956, 2022). "T helper follicular cells from CD4+ T-cell subsets help B cells and induce antibody responses, thus playing an important role in anti-tumor immunity." (PMID 35305616, 2022). "We have shown in animal models the efficient stimulation of citrullinated epitope specific CD4 T cells resulting in dramatic elimination/regression of tumours." (PMID 36544781, 2022). "Constraining FGFR pathways by a selective FGFR inhibitor (FGFRi) Erdafitinib significantly suppressed tumor growth with increased CD3+ (CD4+ and CD8+) T cell infiltration in immunocompetent BALB/c mice bearing EMT6 or 4T1 tumors." (PMID 35832090, 2022).
tumor (continued). "Improved understanding of the critical implication of CD4+ T cells in antitumor immune response has undermined the classical notion of enhancing only CTL with antitumor activity to induce tumor rejection and improve cancer patients’ survival." (PMID 35008422, 2022). "When he presented after almost 3 years, his CD4 count had dropped to 8 cells/μL, while the tumor diameter remained at 5.6 cm3." (PMID 35141174, 2022). "We identified regions within tumor samples in which T cells co-expressed CD4 and GZMB, and tumor cells co-expressed pan-CK and HLA-DR." (PMID 35831288, 2022). "These clinically relevant tumor-activated γδ T cells induced strong antigen-specific CD4+ and CD8+ αβ T-cell responses and prevented immunosuppression mediated by CD4+ CD25+ Treg cells." (PMID 35880177, 2022). "Adding MEKi to BRAFi also increases CD8+ and CD4+ TILs (Homet Moreno, Mok, Comin-Anduix, Hu-Lieskovan, & Ribas, 2016); anti-tumor responses mediated by this combination are T-cell dependent." (PMID 35513054, 2022). "Functional enrichment analysis performed during the current study showed a higher degree of enrichment for immune-related pathways for the low-risk group and that CD4+ and CD8+ T cells are more abundant in tumor infiltration." (PMID 35359880, 2022). "CD4 T cells are important for the development and sustainment of a T cell mediated anti-tumor response." (PMID 35682650, 2022). "By conducting comparative analysis on immune cells between tumor and normal samples, more cells such as Macrophage M0, M1, M2, Tregs and activated CD4 memory T cells were observed to be present in the tumor samples." (PMID 35741779, 2022). "Future studies involving samples from murine models, human tumor organoid models or clinical trials are of great interest to uncover the functional states and regulatory mechanisms of cytotoxic CD4+ TCR-Ts in vivo." (PMID 35928827, 2022). "Naive, memory and regulatory CD4 T-cell populations (Gini = 0.70, 0.64, and 0.57) had many dense foci near the B-cell-enriched regions and sporadic foci elsewhere in the tumor." (PMID 35046414, 2022). "In the immune system, this information comes to the CD4+ T cells in the form of tumor antigenic peptides presented by antigen-presenting cells (APCs), the most prominent members of which are dendritic cells (DCs) and macrophages." (PMID 36123677, 2022). "Inhibition of HIF-1α down-regulated expression of pro-inflammatory factors IL-10, IL-12, PGE2, S-180, TNF-α, and abrogated memory CD4+, CD8+ T cells-mediated suppression of tumor-associated macrophages (TAM)." (PMID 36761171, 2022). "As only 3 patients with HNSCC were in grade III of the tumor, the frequencies of CD4+ T cell subsets were compared in patients with grade I with those with grade II + III of the tumors." (PMID 36376825, 2022). "In contrast, the proportions of CD4+ T lymphocytes gradually decreased from 22.98%, 15.59% 3.31% in peripheral blood, paratumor tissues and tumor tissues, respectively, which was also observed in NK clusters at 13.12%, 3.31% and 2.69%, respectively." (PMID 35562760, 2022). "Another area of study is cellular immunotherapy with natural killer cells stimulated with an IL-15 analog or CD4/CD8 cells stimulated with tumor neoantigens." (PMID 36844955, 2022). "Survival rate analysis was performed based on a tumor volume of 1,000 mm3; interestingly, only depletion of CD4 mimicked the survival rate of the control (**p ≤ 0.01)." (PMID 36545214, 2022). "Recent studies have identified CD39 as a marker of tumor-antigen specificity in conventional CD4+ T cells (Tconv) and found that these cells can be reactivated by anti-PD-1 therapy." (PMID 36003398, 2022). "Inactivation of CD4+ T cells will further cause a decrease in the secretion of IL-2 and IFN-γ, impairing cytotoxic T lymphocyte-mediated tumor killing activity." (PMID 35603146, 2022). "As IL-15 has been shown to strengthen the anti-tumor response, we have modified CD4 CAR to secrete an IL-15/IL-15sushi complex." (PMID 36172388, 2022).
tumor (continued). "Depleting TGF-βR2 in CD4+ T cells halts cancer development due to tissue repair and rebuilding of the tumor vasculature." (PMID 35720407, 2022). "By analysis of various immune components in tumor, we found that the combination treatment was sufficient to augment the infiltration of CD8+ T cells and CD4+ T cells into the tumors, indicating a robust T-cell mediated anti-tumor immunity." (PMID 35013252, 2022). "Immune infiltrate analysis of the tumours showed a decrease in CD4+ T cell and macrophage infiltration in the IL-36RKO tumours in comparison to scramble control tumours." (PMID 35365751, 2022). "iTreg is a highly immunosuppressive, therapy-resistant Treg, which is driven to converse from conventional CD4+ T cell, and can suppress the anti-cancer immune reaction, thus enhancing the tumor development." (PMID 36313434, 2022). "Regulatory T cells are key factors in tumor immune escape, as they can inhibit the activation and differentiation of CD4+ helper T cells and CTLs to induce reactivity against tumor‐expressed antigens through a variety of mechanisms." (PMID 35067006, 2022). "We have already applied the same conditions for simultaneous CD8+ and CD4+ T cell assessment (10 μg/mL EP on day 1 and 50 μg/mL EP to read-out) to monitor tumor antigen-specific T cells in cancer patients." (PMID 36359847, 2022). "T cells in CLL patients, as major supporting cells in the tumor microenvironment and particularly CD4+ T cells, nourish CLL cells through complex cytokine networks or direct contact." (PMID 36059445, 2022). "For example, cancer chemotherapy has been shown to induce cell necrosis that releases immunostimulatory danger signals into the TME and to increase tumor infiltration by cytotoxic CD4+ T cells." (PMID 35269922, 2022). "CD8+/FoxP3+ and CD8+/CD4+ ratios are the most commonly used indicators, indicating the strength of anti-tumor immune activity." (PMID 36209263, 2022). "OX40 has been shown to regulate tumor immunity as a member of the tumor necrosis factor superfamily and is highly expressed by activated CD4, CD8 T-cells and regulatory T-cells (Tregs) and to a lesser extent by neutrophils and natural killer (NK) cells." (PMID 36612271, 2022). "HLA-DR is involved in the suppression of tumour growth, whereby it presents tumour-associated antigens (TAA) that are recognised by CD4+ T cells, which then produce cytokines, such as interleukins and interferon-γ (IFN-γ), to inhibit tumour growth." (PMID 35208514, 2022). "This quantum dot-derivative labeled tumor-derived CD4+Foxp3+ Treg at higher extent than any other tumor-infiltrating T cell population in a mouse model of intracranial tumors." (PMID 35693776, 2022). "The miR-18a high and low tumor specimens (n = 15 each) were further used for IHC labeling with CD4 and CD8." (PMID 35626709, 2022). "CD4+ T cells are associated with the production of IFN-γ and present tumor antigens to CD8+ T cells." (PMID 36229828, 2022). "CD4+ T cell subsets have varied impacts on tumor growth while they play a pivotal helper role in orchestrating cancer immunity." (PMID 35008422, 2022). "Such consistency indicates that integrin expression on CD4+ CD25+ T regulatory cells promotes immune infiltration and impels Tregs to aggregate around tumor cells, thereby causing a local immunosuppressive state via some possible mechanisms." (PMID 36553542, 2022). "Subsequently, the ratio of CD45+cells, CD3+ T cells, CD8+ T cells, CD4+ T cells and Treg cells in the tumor and peripheral blood was analyzed." (PMID 36518768, 2022). "Most cyTCs are CD8+; however, a subgroup of CD4+ cyTCs exists, which can also directly destroy tumor cells by cytolytic action." (PMID 36230402, 2022). "These include the promotion of tumor progression (e.g., the facilitation of tumor cell migration and invasion), the suppression of CD4-positive T cells, and the activation of the mTOR function that stimulates the proliferation of AML cells." (PMID 36142442, 2022).
tumor (continued). "VATS is associated with a lesser postoperative decrease in the numbers of circulating CD3+, CD4+, and CD8+ T cells, which lowers the risk of imbalanced immunoregulation and preserves immunosurveillance, decreasing the risk of tumor growth and recurrence." (PMID 35669251, 2022). "CD4+ Th1 cells amplify cytotoxic T lymphocyte responses by assisting their priming relayed through specific DCs, and target tumor cells either directly through cytolytic mechanisms or indirectly by modulating the tumor microenvironment." (PMID 36059511, 2022). "Considerable research attention has focused on the relationship between the role of local tumor-infiltrating lymphocytes (TILs [CD4+ and/or CD8+ T cells]) associated with FOXP3+ Tregs in the tumor microenvironment and the prognosis of SCC patients." (PMID 35358193, 2022). "The interaction between LAG3 and its ligands promotes tumor escape from apoptosis through the recruitment of tumor-specific CD4+ T cells (through the interaction with MHC class II) and the inhibition of CD8+ T cells’ cytotoxic function by Gal-3 binding." (PMID 36230566, 2022). "CD4+ T cells are differently involved in tumor occurrence and development, but mainly through immunosuppression, by Foxp3+ Treg cells and cytotoxic T lymphocytes (Tc), memory T lymphocytes, and T helper lymphocytes (Th)." (PMID 35321670, 2022). "Of the 4 types of tumor-infiltrating immune cells (TIICs) evaluated, the highest density was found for CD8 lymphocytes in the invasive front (CD8-IF), while the lowest density was found for CD4 lymphocytes in the tumor center (CD4-TC)." (PMID 36526699, 2022). "We have identified the different steps necessary for this outcome to occur; TAMs need to be able to constitutively capture tumor antigens and present them to effector CD4 T cells at the tumor site." (PMID 35903540, 2022). "TRAIL treatment of wild-type mice enhanced tumor growth and increased the number of CD4+ Tregs in the tumors." (PMID 36496977, 2022). "Currently, CD4/CD8 CAR-T cells at a 1:1 ratio have been demonstrated to exert excellent anti-tumor effects." (PMID 35757715, 2022). "By contrast, the frequencies of IFN-γ–producing CD4+ T cells in the tumors were similar between tumor-bearing KO mice and tumor-bearing WT mice." (PMID 35143421, 2022). "After tumour formation, the amounts of CD4+ and CD8+ T cells slightly increased, but in turn, they rapidly decreased as the tumour consistently grew." (PMID 35177112, 2022). "Compared to the isotype control, the low-salt diet, when combined with anti-CTLA4 mAb, induced significant inhibition in tumor progression kinetics, thus suggesting that the LS diet did not impact the inflammatory activation of tumor infiltrating CD4+T cells." (PMID 35741331, 2022). "There were significantly higher levels of CD4 Th lymphocytes in VHL tumours compared to SDHB tumours and the lowest levels of both Th and Tc lymphocytes were observed in PPGLs with underlying SDHB mutations." (PMID 35975974, 2022). "Their association with clinical responses to ICB suggests a potential central role of systemic CD4 T-cell help in facilitating tumor rejection under immunotherapy." (PMID 35954341, 2022). "FACS and IHC analyses showed that recruitment of CD3 + /CD8 + cytotoxic T cells, which suppress cancer cells, increased and that tumor-friendly CD3 + /CD4 + /FoxP3 + T cells decreased upon co-treatment with PLAG + aPD-L1." (PMID 35787261, 2022). "In contrast, an anti-inflammatory response mediated by CD4+/Th2 and M2 TAMs will favor tumor progression." (PMID 36226048, 2022). "Just under 10% of tumor-infiltrating CD4+ T cells expressed FOXP3 by flow cytometry across measured samples." (PMID 35584630, 2022). "The first targeted antigen, CD4, for example, is strongly expressed on both tumor cells and normal cells whereas the second antigen should be tumor specific." (PMID 36059451, 2022).
tumor (continued). "An early study illustrated that the loss of B cells (anti-CD20) significantly enhanced responses to cisplatin, carboplatin, and paclitaxel through the increase of tumor CD4+ and CD8+ T cell infiltration." (PMID 35967441, 2022). "Consistent with our functional results, h219-LLG increased percentages of CD4 memory T cells and inflammatory macrophages, but decreased those of pro-tumor macrophages, Tregs, and plasmacytoid dendritic cells." (PMID 36211388, 2022). "We performed dual IF analyses on tumour sections in which each checkpoint protein was simultaneously immune-stained for CD4 and CD8 lymphocytes." (PMID 36185249, 2022). "Depletion of TGF-βRII in CD4+ T cells inhibited tumor progression, which resulted in tumor cell death in distant avascular regions due to vascular remodeling." (PMID 36534225, 2022). "The correlation of 5 central protein-coding genes with tumor purity and 6 kinds of immune cells (B cells, CD4+ T cells, CD8+ T cells, Neutrphils, Macrophages and Dendritic cells) was further analyzed." (PMID 36524001, 2022). "Here, we demonstrated that the clinical compound UDCA degraded both latent and activated TGF-β, as observed in various tumor cells and CD4+ T cells, indicating that UDCA is a pan-TGF-β inhibitor." (PMID 35701426, 2022). "Collectively, higher rate and effective score of CD8+, CD4+ total, and effector T cells represented a unique tumor immune environment." (PMID 35811317, 2022). "Both the anti-tumor immune response and irAE arise from enhanced host immune reaction, wherein activated pro-inflammatory CD4+T cells infiltrate both tumors and other healthy organs." (PMID 35741331, 2022). "Increased production of IFN-γ by CD4+ T cells were also observed in the tumors of mice bearing 4T1/Ubr5-/-Pdl1-/- tumor." (PMID 35836797, 2022). "Upon closer observation, it was seen that CD4+IFNγ+ population was clearly segregated in two populations based on the number of these cells per gram of tumor." (PMID 35651802, 2022). "Regulatory T cells (CD4+ T cells) also play a critical role in tumor progression by suppressing cytotoxic CD8+ T cell proliferation and favoring cancer cells escape from immunosurveillance." (PMID 35884501, 2022). "In this study, we examined the role and regulation of CD161 expression on tumor-specific CD4+ cells." (PMID 35039463, 2022). "The activation of CD4+T cells by antigen-presenting cells promotes the migration of highly cytotoxic CD8+T cells to the tumor site and plays the role of tumor immune mediators." (PMID 36778600, 2022). "We found that activated tumor-infiltrating lymphocytes were enriched in cluster A, especially activated CD4+ cells, CD8+ T cells, and NK cells." (PMID 35558555, 2022). "The expression of FUBP3 was positively correlated with the expression of CD8+ T cells, CD4+ T cells, and macrophages in tumor tissue, based on immunohistochemistry." (PMID 35413821, 2022). "Several studies found that rHGP exhibited reduced CD8+ immune cells infiltration, and high levels of peri-tumor infiltration by CD4+, CD45RO+, and CD8+ cells would appear in dHGP." (PMID 35785215, 2022). "In different experimental models, neutrophils can exert anti-tumor activities by directly killing tumor cells and activating αβ T cells and CD4+ and CD8+ T cells." (PMID 35203640, 2022). "JHU083 increases infiltration of anti‐tumor CD8+ T cells and Th1 T cells and decreases immune suppressive myeloid‐derived suppressor cells, regulatory T cells, and CD4+ Th17 cells in EGFR‐mutated lung tumors." (PMID 35861366, 2022). "Immunophenotypically, the tumor cells are characterized by CD4 expression in 75% of the cases and positive expression of both CD4 and CD8 markers in 25% of the cases." (PMID 36605429, 2022). "In tumour xenograft tissues, α5-nAChR expression was related to PD-L1, Jab1, pSTAT3, CD4 and granzyme B expression (GB)." (PMID 35971127, 2022).